HOXD9 (homeobox D9)
Diseases named in the same sentence as HOXD9 in open-access papers (continued):
Sharing a sentence is not in itself a finding about the gene and the disease.
tumor (continued). "Kaplan-Meier analysis of the survival curves showed a significantly worse overall survival for patients whose tumors had high HOXD9 levels, indicating that a high HOXD9 tumor protein level is a marker of poor prognosis for patients with GC." (PMID 31547840, 2019). "LV-HOXD9 cell groups was increased compared to that in LV-vector cells, whereas RUFY3 knockdown decreased the proliferation rate and tumor vessel density in the HOXD9-overexpressing group." (PMID 31547840, 2019). "XRCC1 (AUC=0.847), SOX4 (AUC=0.985), and HOXD9 (AUC=0.767) indicated that these three genes could be ideal biomarkers to distinguish LGG from non-tumor tissues." (PMID 38217545, 2024). "Our findings suggest that HOXD9 has pro-tumor activity in ATC and acts as a cancer promoter." (PMID 37974228, 2023). "This study provides novel insights into the tumor-promoting role of HOXD9 in ATC." (PMID 37974228, 2023). "In addition to its role in the cell cycle, HOXD9 was demonstrated to suppress apoptosis of tumor cells." (PMID 36907878, 2023). "Consequently, the knockdown of HOXD9 significantly suppressed the tumor growth, as revealed by the impaired increase of tumor volume on days 18, 21, and 24 after inoculation as well as the reduced tumor weight in the si-HOXD9 group." (PMID 37974228, 2023). "Moreover, HOXD9 silencing induced apoptosis, inhibited proliferation, cell cycle progress, migration and invasion of these tumor cells." (PMID 36907878, 2023). "We established an orthotopic mouse thyroid model using 8505c cells expressing si-HOXD9 to determine if HOXD9 silencing could affect tumor growth in vivo." (PMID 37974228, 2023). "Accumulating evidence has suggested the contribution of HOXD9 in initiation and evolution of tumor." (PMID 36907878, 2023). "Delivery methods that target anti-HOXD9 agents preferentially to tumor sites could also reduce off-target effects." (PMID 37974228, 2023). "Thus, if HOXD9 inhibitors can be clinically applied, they are expected to exert their anti-tumor effects through various pathways." (PMID 34572841, 2021). "Next to investigate whether HOXD9 could physically bind to the RUFY3 promoter in vivo, we performed chromatin immunoprecipitation (ChIP) -qPCR assays in human tumor cell lines expressing endogenous HOXD9." (PMID 31547840, 2019). "The expression pattern of HOXD9 mRNA in normal and tumor tissues." (PMID 31547840, 2019). "The HOXD9 protein may enhance the malignant properties of tumor cells via its transactivation of the RUFY3 proto-oncogene." (PMID 31547840, 2019). "Furthermore, as CD8+ T cells play a central role in anti-tumor immunity, HOXD9 may improve the efficacy of immunotherapy by enhancing their function." (PMID 39980564, 2025). "In addition, we identified XRCC1 (AUC=0.847), SOX4 (AUC=0.985), and HOXD9 (AUC=0.767) as three molecules that could be ideal biomarkers to distinguish LGG from non-tumor tissues." (PMID 38217545, 2024). "However, the effect of HOXD9 on tumor microenvironment, and whether HOXD9 acts as a specific molecular for targeted therapy of NSCLC need further exploration." (PMID 36907878, 2023). "As HOXD9 is an important transcription factor promoting tumor proliferation, we examined the correlation between HOXD9 mRNA levels and proliferation markers PCNA, Ki-67 as well as cell cycle related genes CCNA2 and CCNB1 to validate whether HOXD9 can facilitate ATC proliferation." (PMID 37974228, 2023). "However, the specific role of HOXD9 methylation in tumor progression needs to be further studied." (PMID 32536823, 2020). "Therefore, HOXD9 may play a critical role in RUFY3-mediated tumor growth and metastasis in vitro and in vivo." (PMID 31547840, 2019). "Both HOXD9 mRNA and protein were found to be significantly elevated in most ATC tumor tissues when compared to normal tissues via bioinformatics analysis." (PMID 39858044, 2025).
tumor (continued). "A linear regression analysis was used to determine the correlation between HOXD9 expression and pathological characteristics, where high HOXD9 expression was positively correlated with the TNM stage, tumor size, and distant metastasis." (PMID 39858044, 2025). "We found that HOXD9 was typically overexpressed in ATC tissues, had a favorable correlation with clinicopathological characteristics (tumor size, distant metastasis, and TNM stage), and was an independent prognostic predictor for ATC patients." (PMID 37974228, 2023). "In this study, we discovered that PSMB8 had a similar molecular profile to HOXD9 in ATC and they were both upregulated in tumor tissue." (PMID 37974228, 2023). "Western blotting and qPCR results indicated that HOXD9, PABPC1, and PAK1 were usually upregulated, whereas PAXIP1-AS1 was frequently downregulated in the 15 tumour samples examined compared to that in the paired paracancerous tissues from the same patient." (PMID 37225681, 2023). "The protein levels of HOXD9, Ki-67, and CD31 in tumors were estimated by IHC and a fluorescence TUNEL assay was used to determine cell apoptosis in the same tumor tissues." (PMID 37974228, 2023). "HOXD9 has been shown to promote HCC epithelial-mesenchymal transformation and tumor cell metastasis." (PMID 36536232, 2022). "In TNBC, miR205-5p functions as a tumor suppressor and predominantly targets oncogenic genes, including CLDN11, HOXD9, and HMBG." (PMID 35804829, 2022). "In conclusion, the current study suggests that HOXD9 is overexpressed in CRC and increases tumorigenicity and tumor proliferation." (PMID 32281284, 2020). "We identified that HOXD9 directly regulates RUFY3 expression in GC and sequentially promotes tumor proliferation, metastasis and invasion." (PMID 31547840, 2019). "EMT, as well as tumor migration and invasion of HCC cells is promoted by the oncogene HOXD9; while ZEB1 knockdown inhibits these HOXD9-induced effects." (PMID 27412382, 2016). "HOXD9 may affect the epigenetic state of CD8+ T cells through similar mechanisms, thereby enhancing their anti-tumor activity." (PMID 39980564, 2025). "After confirming the efficiency of HOXD9 overexpression by western blotting, we determined whether PAXIP1-AS1 was involved in HOXD9-mediated tumour cell migration, invasion, and EMT." (PMID 37225681, 2023). "Recently, HOXD9 was found to be highly expressed in tumor samples from NSCLC patients and had a significant negative correlation with patients’ overall survival." (PMID 36907878, 2023). "Furthermore, N-cadherin and vimentin levels were attenuated after HOXD9 downregulation, while E-cadherin was upregulated, suggesting that HOXD9 activates EMT to enhance tumor metastasis." (PMID 36262353, 2022). "The result showed that, relative to paired adjacent noncancerous tissues, HOXD9 was markedly increased in the eleven tumor specimen." (PMID 32281284, 2020). "HOXD9 is overexpressed in CRC and increases tumorigenicity and tumor proliferation." (PMID 32281284, 2020). "Recent studies showed that homeobox D9 (HOXD9) can increase cell metastasis through the TGF-β1-induced EMT63, and the NMYC interactor (NMI) can upregulate signal transducer and activator of transcription 1 (STAT1) and then promote tumor cell proliferation via the TGF-β/Smad pathway." (PMID 36927770, 2023). "Also, ectopic HOXD9 expression influences EMT and tumor spread both in vivo and in vitro." (PMID 32281284, 2020). "HOXD9 was significantly downregulated in tumors with high expression levels of DKK1 and upregulated in tumors compared to controls, indicating that it could be involved in tumor progression through aberrant activation of the Wnt signaling pathway." (PMID 32224864, 2020). "However, serum cfDNA methylation of HOXD9 in human cancer and its application as a tumor biomarker has not been reported." (PMID 30832707, 2019). "Also, miR-205 could down-regulate HOXD9 expression to suppress EMT and tumor development." (PMID 32495824, 2020).
cancer (26 papers, 2010 to 2025). A tumor composed of atypical neoplastic, often pleomorphic cells that invade other tissues. "Strategies to enhance the selectivity of HOXD9 targeting include the development of inhibitors against mutated forms of the protein found specifically in cancer cells." (PMID 37974228, 2023). "According to recent studies, HOXD9 plays an important role in a variety of clinical processes and might be a valuable diagnostic and prognostic indicator for cancer patients." (PMID 37974228, 2023). "Furthermore, HOXD9 upregulation caused a reduction in E‐cadherin in cancer tissues by q‐PCR assay." (PMID 32281284, 2020). "Consistent with the reported oncogenic role of HOXD9 in other cancers, our study suggested that knockdown of HOXD9 induced proliferative suppression, cell cycle arrest, apoptosis, migratory suppression and invasive repression in two human NSCLC cells." (PMID 36907878, 2023). "The key insight from this research is that HOXD9 is a cancer-promoting factor that is significantly expressed in ATC and high levels of HOXD9 expression are associated with a dismal prognosis for survival of ATC patients." (PMID 37974228, 2023). "We also examined HOXD9 protein expression in NSCLC and para-NSCLC tissues from independent hospital cohorts via western blot, which showed that HOXD9 protein expression was remarkably increased in cancer tissues." (PMID 36907878, 2023). "Previous studies indicate that HOXD9 participates in the development and progression of certain cancers." (PMID 37225681, 2023). "Studies have shown that HOXD9 is highly expressed in diverse cancers, which predicts a dismal prognostic outcome." (PMID 36262353, 2022). "It has been demonstrated that HOXD9 was strongly expressed and functioned as an oncogene to promote epithelial-mesenchymal transition and cancer metastasis in HCC." (PMID 36397165, 2022). "Although there is an inconsistency between two recent studies and our data, the overexpression of HOXD9 in different cancers agrees with the hypomethylation of this gene in our findings." (PMID 34452548, 2021). "Semiquantitative scoring showed that HOXD9 protein was expressed at significantly higher levels in cancer tissues than that in adjacent normal gastric mucosa tissues by TMA assay." (PMID 31547840, 2019). "A previous report showed that most cancers are associated with deregulation of the MAPK/ERK (ERK, JNK, and p38) signaling pathways; thus, we explored the mechanism of HOXD9’s effect on proliferation and migration in GC cells." (PMID 31547840, 2019). "The effect on cell growth, invasion, and metastasis also indicates that HOXD9 functions as an oncogene in cancer cells." (PMID 31547840, 2019). "Overexpression of HOXD9 in cancer cells augmented the neoplastic phenotype of mucinous ovarian cancer." (PMID 27703207, 2016). "In contrast, the genes FOXL2 and HOXD9 were significantly downregulated in small putative cancer stem cells in comparison to “healthy” small stem cells; their expression was quite comparable to hESCs but not to fibroblasts." (PMID 27703207, 2016). "HOXD9 has been shown to promote cancer development via transcriptional activation of oncogenes, such as RUN and FYVE domain containing 3 (RUFY3), Snail family transcriptional repressor 1 (SNAI1), Sodium channel epithelial 1α subunit (SCNN1A) and Hemicentin 1 (HMCN1)." (PMID 36907878, 2023). "Moreover, the expression of HOXD9 increases in diverse cancers and is correlated with patient prognosis." (PMID 36262353, 2022). "HOXD9 has been proved to be expressed abnormally in several kinds of cancers." (PMID 33428601, 2021). "Moreover, Cancer tissues showed higher HOXD9 expression relative to adjacent healthy colon mucosa samples by semiquantitative scoring." (PMID 32281284, 2020). "HOXD9, a Hox family member, is involved in cancer growth and metastasis." (PMID 32281284, 2020). "HOXD9 was considered to promote the growth, invasion, metastasis of cancer cells." (PMID 33083004, 2020).
cancer (continued). "HOXD9 was expressed at high or intermediate levels in cancer cells." (PMID 31547840, 2019). "HOXD9 participates in the development and progression of some cancers." (PMID 31547840, 2019). "Taken together, these results indicate that some homeobox proteins including HOXD9 may contribute to cancer stem cell maintenance in addition to the cell proliferation and/or survival." (PMID 21600039, 2011). "Furthermore, immunohistochemical studies showed no apparent correlation between HOXD9 expression level and WHO grade or MIB-1 index, suggesting that HOXD9 may be expressed in primitive cancer cell populations, including GCSCs in vivo." (PMID 21600039, 2011). "Several crucial transcription factors, including STAT3, HOXD9, and HOXB5, are known to bind to ANGPT2 promoter regions, thereby activating ANGPT2 expression and promoting malignant phenotypes in cancer cells 58-60." (PMID 39309430, 2024). "Homeobox D9 (HOXD9), a member of the HOX family of transcription factors, plays a driver role in development of multiple cancers." (PMID 36907878, 2023). "Real-time PCR was performed to check the methylation difference of HOXD9, ZNF154, BCL9, TDRD10, and ANKRD53 genes between the cancer cases and controls." (PMID 34452548, 2021). "The fact that Hox genes such as HOXD10, HOXA9, HOXD9, HOXD13 are strongly upregulated in Huh6 cells on the CAM reflect a profound reprogramming of cancer cells in a permissive, growth promoting in vivo microenvironment." (PMID 29662633, 2018). "The other HOX genes that are notably upregulated in SK-OV3 cells (but generally not OV-90 cells) have previously been shown to be upregulated in other cancers, including HOXA13, HOXB5, HOXB9 and HOXD9." (PMID 20219106, 2010). "Moreover, both HOXD9 and RUFY3 were highly expressed in cancer cells but not in normal gastric tissues, with their expressions being positively correlated." (PMID 31547840, 2019).
HOXD9 also shares sentences with these, for which no sentence is quoted: brain tumor (3 papers); thymic epithelial tumors (2); anaplastic thyroid carcinoma (1); breast tumor (1); cognitive deficits (1); developmental dysplasia of the hip (1); esophageal squamous cell carcinoma (1); insulinoma (1); lung adenocarcinoma (1); medulloblastoma (1); mucinous ovarian cancer (1); oligodendroglioma (1); papillary thyroid carcinoma (1); poorly differentiated thyroid carcinoma (1); prostate carcinoma (1); Sertoli Cell-Only Syndrome (1); squamous cell carcinoma (1); teratoma (1); thymic carcinoma (1); Venous thrombosis (1).